SGK3 (serum/glucocorticoid regulated kinase family member 3)
Diseases named in the same sentence as SGK3 in open-access papers (continued):
Sharing a sentence is not in itself a finding about the gene and the disease.
prostate carcinoma (9 papers, 2011 to 2022). A carcinoma that arises from epithelial cells of the prostate gland. "In keeping with this, SGK1, SGK2, and SGK3 are rarely mutated in prostate cancer (≤0.41%), whereas amplification occurs in up to 2.5%, 2.0%, and 20.3% of cases respectively." (PMID 32630372, 2020). "In prostate cancer, SGK3 is an androgen receptor transcriptional target and promotes cancer cell proliferation." (PMID 33613114, 2021). "Research has shown that dihydrotestosterone (DHT) can upregulate SGK3 expression via androgen receptor (AR) and promote the proliferation of prostate cancer cells." (PMID 30108027, 2019). "Of note, the frequency of SGK3 gene amplification is particularly high in the SUC2/PCF IDT metastatic prostate adenocarcinoma dataset, underlining the need for future studies to establish how SGKs contribute to prostate cancer and metastatic progression." (PMID 32630372, 2020). "The SGK3 gene has been reported to be an oestrogen or androgen receptor transcriptional target in ER‐positive breast cancer cells and in androgen receptor (AR)‐positive prostate cancer." (PMID 27481935, 2016). "Common genetic alterations within the three prostate cancer datasets analyzed were observed in PTEN, DEPTOR, SGK3, FOXO1/3, MAP3K7, RRAGD, SESN1, PIK3CA, PIK3C2B, and PDPK1." (PMID 32630372, 2020).
melanoma (8 papers, 2015 to 2023). A malignant, usually aggressive tumor composed of atypical, neoplastic melanocytes. "More recently, some unexpected findings have indicated that INPP4B is significantly upregulated, and plays an oncogenic role in AML, melanoma and colon cancer by activating SGK3, and that it is associated with patient prognosis." (PMID 33879096, 2021). "Following these studies, another group showed that SGK3 together with PDK1 are implicated in melanomas harbouring BRAF mutations and wild type PTEN, which in fact account for more than half the cases of melanomas occurrence." (PMID 29064423, 2017). "In this context, INPP4B has already been described as an oncogenic driver through phosphorylation and activation of SGK3 in a subset of melanoma and colon carcinoma." (PMID 36993823, 2023). "Our results extended this observation by showing that SGK3 similarly played a role in proliferation of wild-type BRAF melanoma cells (Mel-RM and ME4405) and melanocytes, at least when the upstream signal was driven by INPP4B." (PMID 26573229, 2015). "Collectively, these results indicate that INPP4B activates PI3K/SGK3 signalling to drive melanoma cell proliferation independently of Akt." (PMID 26573229, 2015). "While INPP4B was upregulated in a subset of melanomas, knockdown of INPP4B caused reduction in SGK3 activation, which led to inhibition of proliferation of melanoma cells in vitro and retardation in melanoma growth in a xenograft model." (PMID 26573229, 2015). "Here we report that INPP4B can function as an oncogenic driver through activation of serum- and glucocorticoid-regulated kinase 3 (SGK3) in melanoma." (PMID 26573229, 2015). "In this report, we provide evidence that INPP4B is upregulated in a subset of melanomas and plays a role in melanoma cell proliferation independently of Akt through activating PI3K/SGK3 signalling." (PMID 26573229, 2015). "In particular, a recent report demonstrated an important role of SGK3 in promoting mutant BRAF melanoma growth." (PMID 26573229, 2015). "The role of inhibition of SGK3 in suppression of melanoma xenograft growth was confirmed by transplanting INPP4B stable knockdown Mel-RM cells co-introduced with myr-SGK3 into nu/nu mice." (PMID 26573229, 2015). "Of particular interest, SGK3 has recently been reported to contribute to the growth of mutant BRAF melanomas." (PMID 26573229, 2015). "Apart from SGK1, SGK3 also holds a key role in melanoma resistance to PI3K/Akt inhibition." (PMID 29064423, 2017). "Collectively, these results identify upregulation of INPP4B as an oncogenic mechanism through activation of SGK3 in a subset of melanomas, with implications for targeting INPP4B and restoring miR-494 and miR-599 as novel approaches in the treatment of melanomas with high INPP4B expression." (PMID 26573229, 2015). "Indeed, SGK3 activation (phosphorylation) was elevated in melanoma cell lines expressing relatively high levels of INPP4B compared with those with low levels." (PMID 26573229, 2015). "Indeed, overexpression of miR-494 or miR-599 downregulated INPP4B, reduced SGK3 activation, and inhibited melanoma cell proliferation, whereas introduction of anti-miR-494 or anti-miR-599 upregulated INPP4B, enhanced SGK3 activation, and promoted melanoma cell proliferation." (PMID 26573229, 2015). "Inpp4b was described as a melanoma tumor suppressor via AKT regulation and an oncogene based on its role in activating SGK3." (PMID 35075772, 2022). "Several studies have demonstrated that SGK3 contributes to INPP4B-mediated cell proliferation in colon cancer and a subset of melanomas cells." (PMID 29343273, 2018). "Noticeably, INPP4B-mediated melanoma cell proliferation was not related to activation of Akt, but was mediated by SGK3." (PMID 26573229, 2015).
melanoma (continued). "In support, examination of representative fresh melanoma isolates with various levels of INPP4B showed that melanomas with high, intermediate, and low expression of INPP4B displayed progressively decreasing levels of phosphorylated (activated) SGK3." (PMID 26573229, 2015). "Although shRNA knockdown of INPP4B did not impinge on phosphorylation of SGK1, it inhibited SGK3 activation in Mel-RM and ME4405 cells, suggesting that INPP4B preferentially affects SGK3 activation in melanoma cells." (PMID 26573229, 2015).
colon carcinoma (7 papers, 2018 to 2023). "That is, in colon cancer, INPP4B promotes cell proliferation through SGK3 phosphorylation of AKT." (PMID 36147923, 2022).
glioblastoma (5 papers, 2018 to 2021). The most malignant astrocytic tumor (WHO grade IV). "SGK3 has been reported to be an important tumor-promoting gene and the target gene of miR-212-3p in glioblastoma cells." (PMID 30250399, 2018). "A recent report revealed that SGK3 plays a vital role in glioblastoma as the target gene of miR-212-3p." (PMID 30250399, 2018). "It inhibited proliferation of glioblastoma by inhibiting SGK3, instead of inhibiting VEGF signal." (PMID 33187481, 2020). "Moreover, SGK3 has been recently published as the target gene of miR-212-3p in glioblastoma cells." (PMID 30250399, 2018).
ovarian cancer (4 papers, 2015 to 2021). A primary or metastatic malignant neoplasm involving the ovary. "Here the authors show that p85β promotes AXL protein stability, which in turn activates p110 to induce PDK1/SGK3 signaling, and therapeutically, p85β-expressing ovarian cancer cells are sensitive to AXL inhibition." (PMID 32385243, 2020). "Namely, CA125 promotes the migration of ovarian cancer cells by reducing DKK1 expression and activating the SGK3/FOXO3 pathway." (PMID 33613114, 2021). "Here we report that p85β signals through its upstream kinase AXL, which in turn activates p110 to induce PDK1/SGK3 signaling, establishing the mechanistic basis for targeting AXL in PIK3R2-amplified ovarian cancer." (PMID 32385243, 2020). "Our results demonstrated that CA125 via the MSLN/DKK1/SGK3/FOXO3 pathway accelerates cell migration, and targeting mesothelin may potentially be utilized in ovarian cancer therapy." (PMID 33613114, 2021). "Importantly, p85β-overexpressing ovarian cancer cells demonstrated coordinated enhanced phosphorylation of PDK1, SGK3, and NDRG1." (PMID 32385243, 2020).
cervical carcinoma (3 papers, 2018 to 2023). A carcinoma arising from either the exocervical squamous epithelium or the endocervical glandular epithelium. "Analysis of UALCAN data showed that PDK1 and SGK3 were over-expressed in cervical cancer compared with normal cervix." (PMID 33311486, 2020). "We found that overexpression of INPP4B diminished the activity of SGK3 by decreasing its phosphorylation in cervical cancer cells." (PMID 29516642, 2018). "It has, however, been shown that in cervical carcinoma cells INPP4B overexpression reduces the phosphorylation of both AKT and SGK3, sharing structural and functional similarities." (PMID 36993823, 2023). "It has been shown that in cervical carcinoma cells INPP4B overexpression reduces the phosphorylation of AKT and SGK3, sharing structural and functional similarities." (PMID 36993823, 2023). "In conclusion, INPP4B impedes the proliferation and invasiveness of cervical cancer cells by inhibiting the activation of two downstream molecules of the PI3K pathway, AKT and SGK3." (PMID 29516642, 2018). "Our findings confirmed INPP4B as a tumour suppressor in cervical cancer by regulating AKT and SGK3 activities in various cervical cancer cell lines." (PMID 29516642, 2018). "INPP4B impedes the tumorigenic phenotypes of cervical cancer cells by inhibiting the activation of two downstream molecules of the PI3K pathway, AKT and SGK3." (PMID 29516642, 2018).
chronic kidney disease (3 papers, 2023 to 2025). Impairment of the renal function secondary to chronic kidney damage persisting for three or more months. "In the transition from acute kidney injury (AKI) to chronic kidney disease (CKD), the SGK3/TOPK signaling pathway has been shown to exhibit a counteractive effect, promoting fibrosis in renal tubular epithelial cells and CD206 M2 macrophage polarization." (PMID 40826334, 2025).
liver cancer (3 papers, 2018 to 2019). An epithelial or non-epithelial malignant neoplasm that arises from the liver. "Furthermore, in depth investigations should be aimed at identifying the molecular mechanisms and related pathways whereby SGK3 contributes to hepatocarcinogenesis as well as to an unfavorable patients’ outcome in liver cancer." (PMID 30975125, 2019). "To investigate whether prolonged treatment of liver cancer cells with PI3K inhibitors could promote expression and activation of SGK3, we treated cells with ZSTK474 in a time gradient (0 h, 4 h, 8 h, 24 h, 48 h, and 72 h)." (PMID 29940988, 2018).
multiple myeloma (3 papers, 2015 to 2021). "We conclude that it is unlikely that SGK3 plays a significant role for oncogenic signalling in multiple myeloma." (PMID 25837824, 2015).
acute kidney injury (2 papers, 2023 to 2025). Sudden and sustained deterioration of the kidney function characterized by decreased glomerular filtration rate, increased serum creatinine or oliguria. "Since abnormal accumulation of CD206+ M2 macrophages and profibrotic TECs are key points for accelerating the transition from AKI to CKD, we further examined whether the SGK3/TOPK signaling pathway was linked to renal failure recovery." (PMID 37361201, 2023).
breast tumor (2 papers, 2017 to 2019). "Moreover, Xu studied SGK3 expression in 1340 human breast tumors and found that SGK3 plays an important role in AKT-independent oncogenic signaling." (PMID 30108027, 2019).
colorectal cancer (2 papers, 2019 to 2025). A primary or metastatic malignant neoplasm that affects the colon or rectum. "This tissue-specific pattern contrasts with a previous report that SGK3 promotes AA synthesis in colorectal cancer cells." (PMID 40767604, 2025).
depression (2 papers, 2022). "SGK3 could also regulate the activity of Na+/K+-ATPase in neurons, the osmotic pressure and transmembrane potential inside and outside neurons, and maintaining integrity and excitability of neurons, and is related to depression." (PMID 36531961, 2022).
Hypertension (2 papers, 2018 to 2022). The presence of chronic increased pressure in the systemic arterial system. "In Xenopus oocytes, SGK3 could up-regulate Na+/K+-ATPase activity, which provides power for cardiac contraction and is related to obesity, diabetes, hypertension, and cardiac insufficiency." (PMID 36531961, 2022). "In contrast, there were no significant different in SGK2 and SGK3 mRNA in spleen among the four groups of mice, suggesting that neither of them may not be involved in AngII-induced hypertension." (PMID 30524295, 2018).
leukemia (2 papers, 2018 to 2023). A malignant (clonal) hematologic disorder, involving hematopoietic stem cells and characterized by the presence of primitive or atypical myeloid or lymphoid cells in the bone marrow and the blood. "Considering the activation of SGK3 in NPM1-mutated leukemia cells, we assessed the role of SGK3 in INPP4B-mediated cell proliferation." (PMID 29343273, 2018). "Previous reports and the present study suggest that INPP4B provides a survival advantage through the activation of SGK3 in NPM1-mutated leukemia cells." (PMID 29343273, 2018). "In summary, for the first time to our knowledge, our data suggest that overexpression of INPP4B promotes NPM1-mutated leukemia cell proliferation through SGK3 activation." (PMID 29343273, 2018). "Herein, we report that INPP4B is frequently upregulated in NPM1-mutated AML, and promotes leukemia cell survival in a SGK3-dependent and AKT-independent manner." (PMID 29343273, 2018). "This suggests that upregulation of INPP4B/SGK3 was at least partially caused by NPM1-mA expression in leukemia cells." (PMID 29343273, 2018). "To explore the potential mechanisms by which INPP4B contributes to cell proliferation in NPM1-mutated leukemia, we performed siRNA-mediated knockdown of INPP4B in OCI-AML3 cells, and the phosphorylation (activation) of SGK3 and AKT was then monitored." (PMID 29343273, 2018). "Our results indicate that INPP4B promotes leukemia cell survival via SGK3 activation, and INPP4B might be a potential target in the treatment of NPM1-mutated AML." (PMID 29343273, 2018). "Collectively, these findings support the hypothesis that INPP4B activates SGK3 signaling, to promote cell proliferation in NPM1-mutated leukemia." (PMID 29343273, 2018). "Thus, in addition to SGK3, the other potential mechanisms underlying oncogenic role of INPP4B in NPM1-mutated leukemia cells needs to be determined." (PMID 29343273, 2018). "Along this line, INPP4B knockdown leads to a reduction in p-SGK3 levels, but did not influence AKT activation in NPM1-mutated OCI-AML3 acute myeloid leukemia cells and INPP4B expression is not correlated with alterations in AKT phosphorylation in leukemia, suggesting an AKT-independent mechanism." (PMID 36993823, 2023).
Obesity (2 papers, 2022 to 2025). Accumulation of substantial excess body fat. "SGK3 deficiency impaired adipocyte differentiation both in vitro and in vivo, and consequently ameliorated glucocorticoid-induced obesity in a mouse model." (PMID 40767604, 2025). "SGK3 deficiency in adipocyte progenitors improves DEX-induced obesity." (PMID 40767604, 2025). "Given the role of SGK3 in adipogenesis and DEX-induced obesity, we questioned whether SGK3 deficiency could improve overnutrition-induced adipogenesis and obesity." (PMID 40767604, 2025). "Overall, these results suggest that pharmaceutical targeting of SGK3 can attenuate HFD-induced obesity." (PMID 40767604, 2025). "Because one of the metabolic side effects of glucocorticoids is to promote obesity, we then evaluate the function of SGK3 in regulating adipose tissue under glucocorticoid treatment in vivo." (PMID 40767604, 2025). "Our data reveal that Sgk3-KO mice exhibit substantial protection against chronic glucocorticoid-induced obesity while remaining sensitive to glucocorticoid’s immunosuppressive effects." (PMID 40767604, 2025). "More importantly, pharmaceutical targeting of SGK3 attenuated HFD-induced obesity in mice, and the role of SGK3 in regulating adipogenesis was conserved between humans and mice." (PMID 40767604, 2025). "To investigate the potential role of SGK3 in protecting against DEX-induced obesity within mature adipocytes, we created mature adipocyte–specific Sgk3-KO mice by breeding Adipoq-Cre mice with Sgk3fl/fl mice." (PMID 40767604, 2025). "SGK3 deficiency protected mice from DEX- and HFD-induced obesity." (PMID 40767604, 2025). "Pharmaceutical targeting of SGK3 attenuates HFD-induced obesity in mice." (PMID 40767604, 2025). "Moreover, our results from Sgk3-KO mice showed protection against glucocorticoid-induced obesity while retaining sensitivity to glucocorticoids’ immune suppression effects, highlighting SGK3 as a potential therapeutic target for addressing the metabolic side effects of glucocorticoids." (PMID 40767604, 2025). "Next, we studied whether pharmaceutical inhibition of SGK3 could improve obesity." (PMID 40767604, 2025). "Sgk3-KO mice were resistant to obesity induced by glucocorticoid or a high-fat diet, and proteolysis targeting chimeras (PROTAC) targeting SGK3 reduced adipogenesis in both obese mice and in a thyroid eye disease cell line." (PMID 40767604, 2025). "The marked metabolic benefits conferred by SGK3 inhibition under both DEX and HFD challenge establish it as a promising therapeutic target for glucocorticoid-induced and obesity-related metabolic disorders." (PMID 40767604, 2025). "To monitor the development of obesity, we fed mice an HFD for 2 weeks, followed by vehicle or SGK3 PROTAC injections every 2 days." (PMID 40767604, 2025). "In vitro, SGK3 could increase SGLT1 activity by phosphorylating Nedd4-2 and accelerate glucose absorption, which is related to diabetes and obesity." (PMID 36531961, 2022). "Thus, SGK3 inactivation protected mice from DEX- and HFD-induced obesity." (PMID 40767604, 2025). "This suggests that targeting SGK3 degradation may have therapeutic potential for metabolic dysfunction in obesity, independent of changes in adiposity." (PMID 40767604, 2025). "Sgk3-KO mice exhibited protection from obesity induced by glucocorticoid or a high-fat diet (HFD), and SGK3 PROTAC also showed anti-adipogenesis effects on HFD-induced obesity, suggesting that inhibiting SGK3 could potentially ameliorate glucocorticoid-induced metabolic defects." (PMID 40767604, 2025).
osteosarcoma (2 papers, 2018 to 2021). A usually aggressive malignant bone-forming mesenchymal neoplasm, predominantly affecting adolescents and young adults. "Above all, we illustrated the pathway diagram of LncRNA SNHG5 / miR-212-3p/SGK3 axis in osteosarcoma." (PMID 30250399, 2018). "The results of transwell assays showed that overexpression of SNHG5 and inhibition of miR-212-3p could extenuate the reduction of invasion, and migration of si-SGK3, which showed LncRNA SNHG5/miR-212-3p/SGK3 axis regulate the progression of osteosarcoma." (PMID 30250399, 2018).
polycystic ovary syndrome (2 papers, 2021 to 2022). A disorder that manifests as multiple cysts on the ovaries. "miR-335-5p has been reported to be involved in granulosa cell proliferation by decreasing SGK3 expression in patients with polycystic ovary syndrome (PCOS)." (PMID 36359113, 2022).
retinoblastoma (2 papers, 2023 to 2024). A malignant tumor that originates in the nuclear layer of the retina. "Thus, recent studies reporting on INPP4B-mediated activation of SGK3 depict INPP4B as an oncogenic driver, whereas our functional studies indicate a tumor suppressive role of INPP4B in retinoblastoma." (PMID 36993823, 2023). "Data gained by our analyses revealed decreased cell viability and tumor development as well as re-sensitization towards etoposide upon PTPRE KD in RB cells, indicating an oncogenic role of PTPRE in chemoresistant retinoblastoma, involving miR631 and SGK3 regulating mechanisms." (PMID 38674157, 2024).
allergic reaction (1 paper, 2022). "In vivo, in sgk3−/− mice, the serum histamine levels measured 30 min after the allergic reaction induced by intraperitoneal injection of anti-DNP IgE and DNP-HSA antigen was significantly lower than that in sgk3+/+ mice." (PMID 36531961, 2022).